PIK3CA (phosphatidylinositol-4,5-bisphosphate 3-kinase catalytic subunit alpha)
Diseases named in the same sentence as PIK3CA in open-access papers (continued):
Sharing a sentence is not in itself a finding about the gene and the disease.
ovarian carcinoma (continued). "Therefore, we compared PIK3CA mutations in tumors and nontumor samples in the publicly available ovarian cancer data from the study." (PMID 34172890, 2021). "Exome sequencing revealed that 79% of lesions (EC and/or DIE) carried mutations, with 26% involving ARID1A, PIK3CA, KRAS, or PPP2R1A, among which PIK3CA and KRAS are frequently altered in ovarian cancer." (PMID 41465243, 2025). "The phosphatidylinositol-4,5-bisphosphate 3-kinase, catalytic subunit alpha (PIK3CA), also called p110 alpha protein, is a class I PI3K catalytic subunit that, at first, was considered to be highly involved in ovarian cancers, playing a role as an oncogene." (PMID 41144441, 2025). "Researchers have demonstrated that oncogenes PIK3CA, MCL1, MYCN, DHFR, and eIF-5A2 were over-amplified via eccDNA in primary ovarian cancers, ovarian cancer cell line UACC-1598 and cervical cancer cell line HeLa, respectively." (PMID 37233789, 2024). "miR-337-3p directly targets PIK3CA and PIK3CB, suppresses the proliferation of epithelial ovarian cancer cells and reverses resistance." (PMID 38539161, 2024). "The NBDep method also identified 43 missense driver genes in ovarian cancer having a significant protein–protein network (p-value = 2.12e−06) where well-known genes such as RHOA, PIK3CA, and ATM are among these genes." (PMID 38195844, 2024). "MYC had the highest frequency of copy number variations (6/21, 29%) in recurrent ovarian cancer patients, followed by RB1 (6/21, 29%) and PIK3CA (3/21, 14%)." (PMID 29797793, 2018). "Genomic alterations (GA) in PIK3CA leads to the hyper-activation of the phosphatidylinositol-4, 5-bisphosphate 3-kinase (PI3K) pathway in more than 20% of ovarian cancer (OC) patients." (PMID 30237504, 2018). "LGSOC is distinct among ovarian cancer histologic subtypes, characterized by inherent chemoresistance and MAPK and PIK3CA signaling pathways, making this study particularly relevant for uncovering specific chemoresistance mechanisms and elucidating the plasticity of these signaling pathways." (PMID 41392193, 2025). "We also analyzed PIK3CA, a frequently amplified oncogene in ovarian cancer, and observed that PIK3CA and CCNE1 amplification are not mutually exclusive." (PMID 37519629, 2023).
ovarian carcinoma (continued). "Driver mutations in KRAS, PIK3CA, PTEN, PPP2R1A, and ARID1A presented as larger clones than non-driver mutations and with similar frequency in lavages from patients with and without ovarian cancer, indicating prevalent somatic evolution in all patients." (PMID 36311816, 2022). "But PIK3CA alterations were more enriched in HRD-negative pan-cancer patients but not in ovarian cancer." (PMID 35578198, 2022). "The differential amplification in PIK3CA, MECOM, and ATR while interesting signals require validation using an orthogonal method and a larger cohort given the high degree of aneuploidy found in ovarian carcinoma." (PMID 33811746, 2021). "Undoubtedly, it is of great importance to elucidate how DHTS regulates PIK3CA transcription, as this may provide direction for the development of more promising DHTS analogues for ovarian cancer treatment." (PMID 32860347, 2020). "The level of BRCA1/2 expression was reported to be downregulated by the PI3K inhibitor, BKM120, in wild-type PIK3CA ovarian cancer cells (OVCA433, OVCAR-5, and OVCAR-8), without the involvement of ERK activation." (PMID 32194423, 2020). "IL-6/STAT3 and PIK3CA inhibition did not reverse platinum chemoresistance in ovarian cancer and IL-6 levels cannot be considered as a marker of sensitivity to platinum-based chemotherapy." (PMID 29930760, 2018). "A study including 140 patients (breast, cervical, endometrial, and ovarian cancers) from phase I program treated with PI3K/AKT/mTOR inhibitors, measured different potential biomarkers (PIK3CA, KRAS, NRAS, and BRAF) to see if a correlation was possible with the response rate of patients." (PMID 28008141, 2017). "However, genetic alterations such as PTEN, a negative regulator of AKT, and PIK3CA, a catalytic subunit of phosphatidylinositol-3-kinase (PI3K), are often found in cancers including endometrial and ovarian cancers." (PMID 26469226, 2015). "In ovarian cancer, ARID1A deficiency alone is not sufficient for promoting tumorigenesis, it requires PIK3CA co-activation." (PMID 26569409, 2015). "About 16–24% of ovarian carcinomas harbour PIK3CA amplification irrespective of a histological subtype and is negatively associated with platinum sensitivity and PTEN over expression." (PMID 23393606, 2013). "For example, while the PIK3CA gene was selected from the 3q26 amplicon as the oncogene for subsequent functional analysis, the PRKCI gene from the same region was proposed by a different group to be the oncogene in ovarian cancer." (PMID 19419571, 2009). "In this study, we tested overexpression of activated wild type PIK3CA in OSE in vivo and in vitro, since it might more closely resemble natural OSE transformation during human ovarian cancer development." (PMID 19172191, 2009). "The implications of oncogene expression on cancer drug resistance remain poorly understood, although there have been over 25 oncogenes including KRAS, ERBB2, PIK3CA, AKT hypothesized to contribute to drug resistance in ovarian cancer through various signalling pathways." (PMID 35545786, 2022). "The MAF of PIK3CA mutation in endometrial glands did neither correlate with endometrial status (proliferative phase, secretory phase, or atrophy) nor did it correlate with FIGO stage in ovarian cancer cases (data not shown)." (PMID 34172890, 2021). "Finally, different molecular markers have low or high expression in Type I vs. Type II ovarian carcinomas, but are rarely totally expressed (PTEN mutation, PIK3CA, KRAS mutation, BRAF mutation) or totally absent in either Type I or Type II EOCs." (PMID 31973035, 2020).
ovarian carcinoma (continued). "The NSCLC tumor harbored an activating mutation of PIK3CA (p.E545K) and the papillary thyroid tumor harbored an activating mutation in BRAF (p.V600E); neither mutation was detected in the ovarian cancer tumor despite high-depth, sensitive targeted panel sequencing." (PMID 27245685, 2016). "Interestingly, PIK3CA, which has been suggested as an oncogene and driver of 3q gain in ovarian cancer, is not within either peak, although it is located in the shoulder region of the 3q26.2 peak." (PMID 19419571, 2009). "Thus, oncogene PIK3CA is significantly upregulated in non-proliferating regions in human ovarian cancer in vivo." (PMID 18335034, 2008). "Nuclear proteins from 2008 ovarian cancer cell line treated with TNF-α were able to shift (bind) oligonucleotide sequences containing the predicted NF-κB binding site of human PIK3CA promoter, but were not able to shift either mutant or mock oligonucleotide sequences." (PMID 18335034, 2008). "Finally, to determine if the genes that display altered mRNA expression levels in ovarian cancer patient samples (PIK3CA, TTN, RYR2, KMT2C, KRAS, PTEN, and ARID1A) have any clinical value, we checked the effect of their expression on recurrence and survival of patients with ovarian cancer." (PMID 32626534, 2020). "Therefore, we could speculate that functional SNPs located in PIK3CA and GSTP1 gene may disrupt transcription factor response elements, and further affect the expression level of PIK3CA and GSTP1 and ultimately affect the occurrence and development of ovarian cancer." (PMID 33273524, 2020). "An increase in the copy PIK3CA gene number evaluated by CISH and SISH methods was also noted in lung, uterine and ovarian cancer, and gastric." (PMID 33287350, 2020).
endometrial cancer (193 papers, 2007 to 2026). Primary or metastatic malignant neoplasm involving the endometrium (mucous membrane that lines the endometrial cavity). "PIK3CA mutations are found in approximately 20–40% of endometrial cancers, predominantly in high-grade tumors and in cancers classified as serous or clear cell subtypes, which are more aggressive and poorly differentiated." (PMID 40072110, 2025). "Targeting PIK3CA mutations with specific inhibitors, such as alpelisib, has shown promising clinical activity in advanced gynecological cancers, particularly in endometrial cancer patients." (PMID 40647429, 2025). "In endometrial cancer, PIK3CA amplification was found to be associated with higher age, FIGO stage and grade, nodal metastasis and myometrial infiltration." (PMID 40422510, 2025). "Alpelisib, a PI3Kα-specific inhibitor, has shown efficacy in cancers harboring PIK3CA mutations, including endometrial cancers, by reducing AKT phosphorylation and downstream signaling." (PMID 40072110, 2025). "The PTEN-PI3K-AKT pathway is frequently altered in gynecological tumors, especially in endometrial cancer, where nearly half of the patients have PIK3CA mutations." (PMID 40740763, 2025). "Mutations or deletions in PTEN are common in endometrial cancers and often co-occur with PIK3CA mutations, occurring in up to 80% of endometrioid endometrial carcinomas and frequently associated with poorly differentiated, aggressive tumors." (PMID 40072110, 2025). "In the SAP, four patients (cohort 1 PIK3CA mutation-positive endometrial cancer, n = 1; cohort 3 ovarian clear cell carcinoma, n = 3) had confirmed PR, suggesting that TAS-117 has antitumor activity in patients with selected advanced solid cancers." (PMID 38411735, 2024). "Among Black patients with endometrial cancer, PIK3CA P539R and H1047R mutations were more and less frequent, respectively, compared to White patients." (PMID 38297963, 2024). "In endometrial cancer, for example, multiple concurrent mutations involving PIK3CA and PTEN frequently coexist, amplifying PI3K/AKT pathway signaling." (PMID 38938274, 2024). "In conclusion, this study demonstrated that the combination of alpelisib and eribulin enhanced antitumor activity in a paclitaxel-resistant, PIK3CA-mutated endometrial cancer preclinical model." (PMID 37835582, 2023). "The combination of alpelisib and eribulin synergistically suppressed the proliferation of paclitaxel-resistant, PIK3CA-mutated endometrial cancer cells." (PMID 37835582, 2023). "Endometrial cancers with PIK3CA mutations have been associated with increased myometrial and lymphovascular invasion." (PMID 36773034, 2023). "Combined treatment with alpelisib and eribulin overcame paclitaxel-resistant, PIK3CA-mutated endometrial cancer cells and reversed the EMT progress." (PMID 37835582, 2023). "The objective of this meta-study was to evaluate how PIK3CA exon 9/20 mutations affect survival in endometrial cancer patients, based on available literature." (PMID 36943861, 2023). "We generated paclitaxel-resistant cell lines from PIK3CA-mutated endometrial cancer cell lines by gradually increasing the concentration of paclitaxel in cell cultures." (PMID 37835582, 2023). "Despite this, it has been suggested that coexistence of both PTEN and PIK3CA mutations in endometrial cancer can carry a synergistic effect, resulting in overactivation of the same downstream pathway." (PMID 37465112, 2023).
endometrial cancer (continued). "Paclitaxel-resistant cells were generated from the PIK3CA-mutated, type I endometrial cancer cell lines HEC1A and HEC1B." (PMID 37835582, 2023). "Based on there being neither therapeutic options for paclitaxel-resistant endometrial cancer nor PI3K inhibitors approved in endometrial cancer, we established a preclinical model with paclitaxel-resistant, PIK3CA-mutated endometrial cancer." (PMID 37835582, 2023). "Several studies have reported that approximately 25–53% of endometrial cancer cases had PIK3CA mutations." (PMID 37835582, 2023). "We found that the combination of alpelisib and eribulin significantly reduced the migratory and invasive capacity of paclitaxel-resistant as well as parental PIK3CA-mutated endometrial cancer cells." (PMID 37835582, 2023). "PIK3CA mutations occur most commonly in endometrial cancer (EC) relative to other cancers, and most ECs have a mutation in the PI3K pathway." (PMID 37170094, 2023). "All studies assessing the impact of mutations in exon 9 and exon 20 of PIK3CA on survival rates of endometrial cancer patients were selected for inclusion." (PMID 36943861, 2023). "have shown the co-existence of PTEN and PIK3CA mutations in endometrial cancers, and these results are reflected by the NGS data in our series: Of the 5 patients in this series who had PTEN mutations, 3 co-exhibited PIK3CA mutations (60%)." (PMID 37465112, 2023). "First, we selected PIK3CA-mutated endometrial cancer cell lines as a parental model to generate acquired paclitaxel resistance." (PMID 37835582, 2023). "Following Cox multivariate regression analysis, PIK3CA was identified as a risk factor for achieving CR in endometrial cancer." (PMID 38023131, 2023). "Understanding the role of PIK3CA mutations in relation to clinical survival in endometrial cancer is essential for further development of selective p110a inhibitors, clinical trials and therapeutic approaches." (PMID 36943861, 2023). "In summary, these results suggest that PIK3CA mutations negatively influence survival outcomes of patients with endometrial cancer, including those with low-grade tumors." (PMID 36943861, 2023). "The disease control rate (DCR) was 61.5% in 13 patients with PIK3CA-mutated endometrial cancer, 80.0% in five patients with AKT-altered endometrial cancer and 37.5% in 16 patients with ovarian clear cell carcinoma." (PMID 36039910, 2022). "One patient with endometrial cancer with PIK3CA and PTEN mutations had a complete response (CR) to the pan-PI3K inhibitor copanlisib in a phase-I study." (PMID 35887235, 2022). "Most endometrial cancer cell lines have one or more mutations and/or copy number alterations in the PIK3CA, PTEN, and KRAS genes." (PMID 34831139, 2021). "Mutations in PIK3CA were also present in all endometrial cancers with somatic mutations in the MMR genes tested (n = 13)." (PMID 33530449, 2021). "The current study was designed by NRG to estimate the therapeutic activity of single-agent copanlisib in the setting of treatment failure with one or more prior regimens for metastatic/recurrent endometrial cancer harboring hotspot PIK3CA mutations." (PMID 31934607, 2020). "In conclusion, GY008 study indicates that single agent copanlisib has limited activity in patients with persistent or recurrent endometrial cancer harboring hotspot PIK3CA mutations." (PMID 31934607, 2020). "Eligible patients had endometrial cancer with endometrioid, serous or mixed histology, a somatic PIK3CA gene mutation, measurable disease, and GOG performance status ≤2." (PMID 31934607, 2020).